IL1B (interleukin 1 beta)
Diseases named in the same sentence as IL1B in open-access papers (continued):
Sharing a sentence is not in itself a finding about the gene and the disease.
tumor (continued). "One such potential mechanism governing therapeutic resistance unveiled in the present study is the previously unrecognized role of neutrophil-derived IL-1β in driving iCAF polarization and CAF-tumor cell IL-6/STAT-3 signaling in the PDAC TME." (PMID 36107485, 2022). "Altogether, these data show that both IL-1β and VEGF-A orchestrate HFHCD-induced tumor growth acceleration through independent mechanisms." (PMID 36104342, 2022). "Levels of periostin, VEGF-A TNFα, IFN-γ, IL-1β and IL-17 were measured using ELISA tests, MVD was assessed on CD34-stained specimens, tumor budding was evaluated on H + E slides, and these data were compared with clinicopathological features of the patients." (PMID 35056404, 2022). "We also identified unique signatures in tumour samples after VV-αCEA TCE treatment, including increased levels of CCL1, IFNγ, IL-1a, IL-1b, TIMP-1, and TREM-1." (PMID 36405739, 2022). "On the contrary, IL-32γ isoform is shown to diminish the levels of cytokines that promote tumor growth such as TNF-α, IL-1β, and IL-6, whereas the levels of IL-10 cytokine, a tumor growth-inhibiting cytokine, were elevated." (PMID 35281008, 2022). "Analysis showed that the three selected pro-inflammation markers (IL1B, IL8, IL6) were significantly higher in the Fusobacterium-high tumor samples, suggesting elevated levels of inflammation in these tumors." (PMID 35252868, 2022). "Unfortunately, EZH or HDAC suppression also induces M1 GAMs secreting IL-1β and IL-6, and activates STAT3 signals in GBM tumor cells, leading to an aggravated inflammatory response in the TME of GBM." (PMID 35572545, 2022). "On the other hand, literature has shown that together with IL-1β or TGF-β, IL-4 can induce the differentiation of antitumor Th9 cells, inhibiting tumor growth." (PMID 36324671, 2022). "The M1 phenotype is activated by Toll-like receptor ligands, and interferon gamma (IFN-γ), produces tumor cytotoxicity by producing pro-inflammatory cytokines such as TNF-α and IL-1β, and inhibits tumor progression." (PMID 35740547, 2022). "Tumor progression can be promoted by these factors through various mechanisms, including IFNγ and IL-17 mediated tumor immune surveillance or the recruitment of immune cells into the tumor microenvironment via TNF-α, IL-1β, and IL-6." (PMID 36012113, 2022). "Astrocytes are also activated by tumor cell-derived TGLI1, MIF, IL-8, IL-1β, and TNF-α, as seen in lung and breast cancer brain metastases." (PMID 36291792, 2022). "Through the secretion of pro-inflammatory cytokines such as IL-6, IL-1β, and TNF-α, macrophages can contribute to tumor-promoting inflammation." (PMID 35565306, 2022). "For the first time, the correlation of the salivary levels of TNF-α, IL-1β, and IL-6 with HER2 status, MCP-1, IL-1β, IL-2, and IL-4 with the hormonal status of the tumor was shown." (PMID 36286034, 2022). "After combined treatment with both anti-IL-1β and anti-PD-L1 antibodies, the number of PD-L1+PMN-MDSCs was reduced in the tumors, blocking tumor progression." (PMID 36131911, 2022). "TAMs are known to contribute to tumor growth, infiltration, and neovascularization via multiple mechanisms, such as secretion of cytokines and growth factors—TGF-β, IL10, IL6, IL1β, pleiotrophin, and EGF." (PMID 35920986, 2022). "We previously determined that tumor derived growth factors and chemokines, such as SDF1α (CXCL12), TGFβ, and IL1β, promote PI3Kγ-mediated integrin α4β1 conformational changes and adhesion to endothelium in circulating myeloid cells during tumor inflammation." (PMID 35365657, 2022). "Various cytokines, including IL-6, IL-1β, IL-10, GM-CSF, and VEGF, secreted mainly in the TME by tumor cells, are involved in the activation of pSTAT3." (PMID 35860573, 2022).
tumor (continued). "Using the Oncomine database, we have previously shown that IL1β expression is increased in tumor tissue as compared with normal prostate tissue and that ARNEG cells in patients with mCRPC express high levels of IL1β while ARPOS cells lack IL1β expression." (PMID 36561929, 2022). "Among these, the expressions of 3 genes (IL6, IL1B, and NLRP3) were found to be downregulated in the tumor group while others were upregulated compared to the adjacent nontumorous group." (PMID 35069975, 2022). "CML-MSCs enhance immunosuppressive MDSCs production and aggregation, promoting tumor progression via upregulating immunomodulatory arginase-1 (Arg-1), IL-6, IL-1β, COX-2, and TNF-α in MDSCs and inhibiting anti-tumor immunity." (PMID 35842634, 2022). "Most genes were highly enriched in tumor tissues, while only 4 genes including ELANE, IL6, IL1B and NLRP3 were upregulated in normal tissues." (PMID 36267972, 2022). "In spleen cell supernatants, IFN-γ, IL-4, IL-1β, IL-6, IL-13, MCP-1, and IL-21 were significantly higher in the tumour-bearing SID animals compared to the healthy controls." (PMID 36010845, 2022). "This analysis found the expression of several potent NFκB activating cytokines in microglia, including interleukin-1β (IL-1β), TNF-α, and TNFSF8, with the corresponding receptors being expressed in tumor cells." (PMID 35803925, 2022). "Meanwhile, IL-1b and TNF-α, as stimulators of NF-κB pathway, both enhanced tumorigenesis in CRC, whereas blockade of the NF-κB pathway inhibited tumor growth." (PMID 35596224, 2022). "Other leukocyte-derived inflammatory cytokines, such as IL1β, TNFα or IL10, attract VEGFC-secreting leukocytes that amplify tumor lymphangiogenic activity." (PMID 36612017, 2022). "Stimulated the secretion of IL-6, IL-1β, and IFN-β;Enhanced infiltration of leukocytes and dramatic tumor growth inhibition." (PMID 35748543, 2022). "In this context, DC chemotaxis to the TME is activated by the ATP released by tumor cell death recognized through purinergic receptors and NLRP3 resulting in IL-1β and IL-18 production." (PMID 36230990, 2022). "Tumor-infiltrating M1-type macrophages (anti-tumorigenesis) secrete proinflammatory cytokines (e.g., IL-1β and TNF-α), whereas tumor-infiltrating M2-type macrophages (pro-tumorigenesis) secrete anti-inflammatory cytokines (e.g., IL-6 and IL-10)." (PMID 36246355, 2022). "GAMs control tumor angiogenesis by sensing hypoxic conditions, producing IL-1β, and increasing VEGF-A expression, which are regulators of vascular permeability and tumor angiogenesis." (PMID 35448036, 2022). "CX3CR1low/− monocytes overexpress IL-1β and high IL-1β level upregulates ICAM-1 and VCAM-1 expression in GBM cells, which support the GSC phenotype and accelerate tumor progression." (PMID 35920986, 2022). "The inflammatory factors IL-1β, IL-8, and TNF-α can alter the tumor microenvironment and promote tumor growth, angiogenesis, and metastasis." (PMID 35188865, 2022). "Three genes (ELANE, NLRP7, and CASP5) were downregulated, whereas seven others (GSDMC, IL1A, NOD2, GZMB, GSDMA, IL1B, and PLCG1) were overrepresented in the tumour group." (PMID 35087586, 2022). "The release of tumor recruitment–soluble factors, such as CXCL8, CXCL1, CXCL5, CXCL7, IL-6, and IL-1β, enhances immunosuppressive neutrophil chemotaxis through CXCR2 sensing, found to be highly expressed in NSCLC patients." (PMID 35874749, 2022). "We showed that KRAS-mutant tumor cells exclusively respond to KRAS blockade in vivo, because the oncogene co-opts host myeloid cells via a C-C-motif chemokine ligand 2 (CCL2)/interleukin-1 beta (IL-1β)-mediated signaling loop for sustained tumorigenicity." (PMID 35327394, 2022).
tumor (continued). "In general, IL-1β and TNF-α are well-known cytokines acting as representative mediators of tumor cytostasis." (PMID 35996139, 2022). "Our findings demonstrate that efferocytosis of tumor AC creates a T cell-independent tumor permissive microenvironment by activating NLRP3 dependent inflammasome signaling and IL-1β secretion." (PMID 36439171, 2022). "As regulated by the primary tumor, MDSCs arrived in the metastatic organs before the tumor cells and conditioned it to promote tumor seeding by secreting b-FGF, IGF-1, IL-10, IL-4, IL-1β, SDF-1, and MCP-1." (PMID 35267547, 2022). "Pro-inflammatory cytokines IL-6, IL-1β and TNF-α were found to be higher in tumor-control group compared to normal control animals." (PMID 35197512, 2022). "In cytokine release syndrome (CRS), the tumor cell DNA released by pyroptotic cells during CAR-T therapy is internalized by macrophages, activating the inflammasomes and releasing bioactive IL-1β, IL-18, and other pro-inflammatory cytokines." (PMID 36376979, 2022). "Chronic inflammation induced by pro-inflammatory cytokines such as IL-1β, IL6, and IL-18, released via pyroptotic cell death, is considered to drive tumor progression and immune evasion." (PMID 35432318, 2022). "Macrophage-derived IL-1β activates the IL-1β/HIF-1α/COX-2 axis, enhancing tumor cell EMT and promoting tumor invasion and metastasis." (PMID 36071472, 2022). "The combination of 5-FU with ICB augmented an inflammatory tumor microenvironment with markedly increased CD8+ T cell activation and upregulation of IFNγ, TNFα and IL-1β signaling." (PMID 35634282, 2022). "Reduced IL-1β receptor binding ability or IL-1β levels reduces the accumulation and suppressive activity of MDSC resulting in augmentation of antitumor immunity and delayed tumor growth." (PMID 35720398, 2022). "For instance, inflammatory cytokines such as IL-1β, IL-6, IL-17, IL-18, IL-23, and TNF-α can lead to tumor growth through activation of pathways such as NF-κB and STAT351–54." (PMID 36085201, 2022). "These transcription factors result in the secretion of pro-inflammatory cytokines that also promote tumor growth, such as TNF-a, IL-1β, and IL-6." (PMID 35053599, 2022). "Tumor cells can change the immune status of the tumor microenvironment by upregulating programmed death-ligand 1 (PD-1), and related inflammatory factors such as TNF-a, IL-6, and IL-1β increase significantly." (PMID 36189281, 2022). "From this analysis, we found that macrophage-derived IL1B showed a high and wide regulatory potential to these EMT genes, putatively via the receptor IL1R1 expressed in tumor cells." (PMID 36423636, 2022). "This TAM subtype also owns a high level of VEGFA, CXCL8, and IL1β, similar to previously reported TAM induced from monocyte with factor-1a stabilization in solid ovarian cancer that promoted tumor inflammation and metastasis." (PMID 35935940, 2022). "Interleukins can have a wide variety of pro- or anti- tumor effects and many have been therapeutically targeted in CRC clinical trials including IL-2, IL-12, IL-11, IL-6, IL-α, and IL-1β." (PMID 35205776, 2022). "It has been demonstrated that hypoxia plays a major role in tumor invasiveness and metastasis process by promoting the HIF-1α/GPER (G protein estrogen receptor) and IL-1β/IL-1R axes." (PMID 36499246, 2022). "In a loop of cytokine signalling, IL-6 from SCs through the STAT3 pathway triggered tumour cell EMT and migration, while tumour-derived IL-1β activated the NF-kappa B pathway in glia and further induced SC cytokine secretion from SCs." (PMID 35269454, 2022). "IL-1β upregulated ESE3 in PSCs through NF-κB activation, and ESE3 was required for PSC activation by tumour cell-derived IL-1β." (PMID 35986089, 2022). "M1 macrophages release proinflammatory cytokines such as IL-1β, IL-6, and TNF-α to activate innate immunity and kill tumor cells." (PMID 35210436, 2022).
tumor (continued). "Corroborating with this study, another group recently showed that IL-1β induced PD-L1 expression in HCC, a phenomenon that contributes to tumor immune resistance in HCC." (PMID 36289606, 2022). "IL-1β, IL-6, CXCL8, CXCL10, and vascular endothelial growth factor comprise the M2 TAMs that contribute to cancer metastasis, immune suppression, and tumor growth." (PMID 36239108, 2022). "After the NLRP3 inflammasome is activated, it causes an inflammatory cascade reaction, leading to the release of pro-inflammatory factors such as IL-1β, IL-18, IL-22, TNF-α, and the activation of inflammation-tumor signaling pathways such as NF-κB." (PMID 35292015, 2022). "The results demonstrated that macrophage-IL1B and macro-WDR74 were activated in low tumor cell microenvironment, which promoted the anti-MM immunity." (PMID 36532059, 2022). "Neutrophil-derived IL-1β emerged as a novel mediator of stromal inflammation, inducing inflammatory CAF polarization and CAF-tumor cell IL-6/STAT-3 signaling in ex vivo co-cultures." (PMID 36107485, 2022). "There is experimental evidence showing that TAMs play an additional role with their direct effect on tumor cells and also through immune system modulation with cytokine secretion (e.g., TNF- α, IL-6, and IL-1β)." (PMID 36077144, 2022). "In both CRC subtypes, the pro-inflammatory cytokines IL1-β, IL-6 and TNF upregulate the chemokines CXCL-1/2/3/5/6/8 in CAFs, monocytes and cancer cells; this attracts CXCR1/2-positive neutrophils to the tumor." (PMID 36611932, 2022). "Myeloid-derived suppressor cells are attracted by inflammatory cytokines (e.g., IL-1β, IL-6, PGE2, and tumor growth factors), increasing their production of S100/calgranulins." (PMID 36411489, 2022). "In further support of the pro-tumor role of the NLRP3 inflammasome, IL-1β neutralizing antibodies were recently found to attenuate lung cancer development in a large clinical trial (CANTOS)." (PMID 35740272, 2022). "GAMs have been shown to release a number of factors that stimulate tumor growth and invasion, including TGF-β, IL-1β, IL-6, stress-inducible protein 1 (STI1), and EGF, by acting on GICs in the perivascular niche and glioma cells." (PMID 35448036, 2022). "After IL-1β, TNF-α, and Shh treatment, tumor growth from the MT-KRAS cell lines SW1990 and Panc-1 was significantly induced compared to the control animals, whereas tumor growth from BxPC-3 cells was not stimulated." (PMID 34046348, 2021). "As cytokines have paracrine action and play an important role in the tumor microenvironment, the cytokine-cytokine receptor pathway was analyzed and found that many anti-inflammatory factors (IL1R2, IL1B, and IL20) were decreased." (PMID 34122668, 2021). "IL-6, IL-1β and TNF-α are secreted at high levels in and around the tumor environment after the exposure of MNPs, which alters the TME and improves immune response." (PMID 34834282, 2021). "In this study, we found that compared with the tumor group alone, the NK-exosome-treated tumor group exhibited a significant decrease in the expression of CD133, Bmi-1, MMP-3, IL-1β, IL-6, and TNF-α." (PMID 34527741, 2021). "The neutrophils secrete several inflammatory, immunoregulatory and angiogenic factors, including NE, PR3, CathG, MMPs, VEGF, Bv8 (prokineticin 2), oncostatin M, IL-1β, TGFβ2, BMP2 and HGF, that modulate the tumor microenvironment and affect tumor growth." (PMID 34572138, 2021). "The result suggests that inflammatory cytokines, especially IL-1β, can influence the activation of the FGF19/FGFR4 signaling pathway in the tumor microenvironment." (PMID 33981224, 2021). "Finally, since multiple soluble mediators, such as TNF-α, IFN-γ, IL-1β, IL-17, and IL-27, induce PD-L1 expression on tumor cells, it may be reasonable to raise the question of whether the expression of certain mediators among them is downregulated by NDRG2 expression." (PMID 34885221, 2021).
tumor (continued). "The NLRC4/IL-1β module was able to promote angiogenesis via up-regulation of VEGFA, which in turn to contributed tumor progression." (PMID 33987528, 2021). "A pro-inflammatory cytokine response was shown to be elicited by PDT in HT29 tumor cells, as seen from the significant overexpression of the pro-inflammatory CXCL8 and IL1B genes in both adhered and detached cells." (PMID 34371724, 2021). "The results revealed significant changes including the increased expression of tumorigenesis-related markers, such as CD133, Bmi-1, VEGF, MMP-3, IL-1β, IL-6, TNF-α, and MDR, as well as the apoptotic markers, Bax and Bcl-xL, in the REM134-driven tumor group." (PMID 34527741, 2021). "After mice were inoculated with specific PDAC cells and developed tumors, they were treated with PBS Shh, IL-1β, or TNF-α, and the tumor size was measured every week." (PMID 34046348, 2021). "The pro-inflammatory cytokine IL-1β is a key mediator within the inflammatory TME, where it is produced by several cell types including fibroblasts, adipocytes, TAM, and tumor cells." (PMID 34064859, 2021). "IL-1b and IL34, which were induced by Pparγ1 are also known to induce a pro-tumorigenic tumor microenvironment (TME) with IL-34 enhancing recruitment and survival of TAM." (PMID 33946495, 2021). "CD163+ TAM distribution in tumor sites is closely related to EMT, possibly because their IL-1β production can enhance EMT, promoting tumor cell migration and invasion." (PMID 33995371, 2021). "After log-transformation, the following biomarkers displayed a normal distribution and statistically significant differences in tumor vs. control (in alphabetical order): APRIL, BAFF, CA19-9, pERK, IL-1β, IL-1RA, IFN-β, IL-26, MMP-2, and TWEAK." (PMID 33846436, 2021). "HPV infection appears to ablate the ability of keratinocytes to express IL-1β; indeed we previously observed low levels of IL-1α and IL-1β in HPV-positive compared to HPV-negative cell lines and tumour biopsies." (PMID 35047989, 2021). "TME in the context of obesity increases tumor-infiltrating myeloid cells with activated NLRC4 inflammasomes, thereby activating IL-1β and driving disease progression through adipocyte-mediated VEGFA expression and angiogenesis." (PMID 34063828, 2021). "Some of these changes are beneficial when it comes to non-tumor-promoting conditions, e.g., the decrease of VEGF, TGFβ, IL6, CXCL1, CXCL9, IL1β, and M2-macrophage-inducing IL4, as well as the increase of immuno-supportive and M1-associated IL12p70 and TNFα." (PMID 34064000, 2021). "Here, we report a IL1β-mediated paracrine loop from tumor cells towards normal resident fibroblasts, that elicits a secretory response in fibroblasts that increases the tolerance of tumor cells to L-OHP and might be responsible for the pool of the iCAFs subset." (PMID 34066976, 2021). "Although tumor inoculation of the 4T1 cell line generated greater levels of TNF-α, IL-1β, IL-6 in the spleen, serum, primary tumor, and liver, the IL-1β cytokine increased only in the cortex and hippocampus." (PMID 34572719, 2021). "In our study, secretion of IL-6, IL-8, MMP-9, PDGF-BB, IL-1β, G-CSF, and CCL-2 by ccRCC immune cells in tumor microenvironment were able to overcome the anti-angiogenic effects of cabozantinib." (PMID 34931665, 2021). "In this study, we focused on the metabolic effect of neutrophils on BC cells and identified IL1β and TNFα as a vital bridge that connected C5RN and tumor cells." (PMID 34312368, 2021). "Furthermore, in murine models, CSCs have been found to recruit and induce pro-tumor phenotypes in neutrophils through the release of RNA contained in exosomes, which travel to the bone marrow interacting with neutrophils, promoting their survival, proliferation, and IL-1β synthesis." (PMID 34503571, 2021).